C5AR1 (complement C5a receptor 1)
Diseases named in the same sentence as C5AR1 in open-access papers (continued):
Sharing a sentence is not in itself a finding about the gene and the disease.
tumor (continued). "As an important part of the complement system, the C5a/C5aR1 activation pathway is implicated in various inflammatory processes, the pathogenesis of immune diseases, and tumor growth." (PMID 36508191, 2023). "Another study found that C5aR1 played a role in mediating the polarization of tumor-associated macrophages in tumor microenvironment to M2 phenotype in CRC metastasis through the NF-κB pathway in mouse models and mouse CRC cells." (PMID 36192575, 2023). "C5a receptor 1 (C5aR1) is associated with various inflammatory processes, the pathogenesis of immune diseases, and tumor growth." (PMID 36508191, 2023). "Up-regulated C5aR1 expression in tumors was usually associated with higher proliferation rate, tumor metastasis, advanced tumor stage and poor prognosis." (PMID 36192575, 2023). "Expression of CCL19 (which expressed a 2.6-fold-change in MCTVT) and C5AR1 (which expressed a 2.28-fold-change in MCTVT) is highly associated with the advanced tumour stage and promotes cell proliferation in several cancers, leading to poor patient outcomes." (PMID 34980125, 2022). "Conversely, mice deficient in C5aR1 or C5aR2 had higher tumor incidence, suggesting a tumor limiting role of these receptors in this particular model." (PMID 35860237, 2022). "The C5a-C5aR1 axis also skews the activation of tumor-associated macrophages (TAM) toward M2 anti-inflammatory phenotypes and enables metastasis in a colon cancer mouse model." (PMID 35860237, 2022). "In agreement with a previous study, our analysis revealed a context-dependent association between C5, C3, C3AR1, and C5AR1 expression and tumor immune infiltration across different cancer types." (PMID 34439277, 2021). "Lastly, we also demonstrated that the expression levels of C3, C5, C3AR1, and C5AR1 were associated with context-dependent chemotherapy, lymphocyte-mediated tumor killing, and immunotherapy outcomes in different cancer types." (PMID 34439277, 2021). "Taken together, these findings demonstrate that increased C5aR1+ neutrophils are associated with tumor progression and poor survival for BC patients." (PMID 34312368, 2021). "Collectively, these correlation analyses established a strong association between C3, C5, C3AR1, and C5AR1 and tumor immune evasion via dysfunctional T-cell phenotypes with a less significant contribution from T-cell exclusion." (PMID 34439277, 2021). "We used multi-omics approaches to evaluate the association of complement signature C3/C5/C3AR1/C5AR1 with tumor immune phenotypes and prognosis across various cancer types." (PMID 34439277, 2021). "Our results demonstrate that the expression levels of C3, C3AR1, and C5AR1 were inversely associated with tumor purity." (PMID 34439277, 2021). "Our results suggest that C3, C5, C3AR1, and C5AR1 are associated with tumor immune evasion via dysfunctional T-cell phenotypes with a lesser contribution of T-cell exclusion." (PMID 34439277, 2021). "Further correlation analysis revealed that C3, C5, C3AR1, and C5AR1 were associated with tumor immune evasion via dysfunctional T-cell phenotypes with a lesser contribution of T-cell exclusion." (PMID 34439277, 2021). "Further analysis revealed that C3, C5, C3AR1, and C5AR1 were associated with tumor immune evasion via dysfunctional T-cell phenotypes with a lesser contribution of T-cell exclusion." (PMID 34439277, 2021). "More importantly, C5 and especially C5ar1 deficiency almost completely prevented tumorigenesis, as determined by the quantification of tumor numbers and size." (PMID 32754267, 2020). "Perhaps the first study on the role of complement in tumor angiogenesis was the work demonstrating significantly reduced tumor growth and reduced vascularization of tumors from C3 and C5aR1-deficient mice in a transgenic model of ovarian carcinoma." (PMID 33271774, 2020).
tumor (continued). "In consistent, the counterpart tissues of C5- and C5ar1-deficient mice were infiltrated with significantly greater numbers of CD8+ T cells compared with the tumor tissues of WT and C3-deficient mice." (PMID 32754267, 2020). "In AOM/DSS-induced CRC mice, we found that the reduction in MDSCs and concomitant increase in CD8+ T cells in the tumor, blood and/or spleen correlated with the preventive effects of C5 and C5ar1 deficiency, and a C5aR1 antagonist on CRC development." (PMID 32754267, 2020). "Our results reveal the underlying mechanism of C3, CR4, and C5aR1 in regulating the polarization of tumor-associated macrophages (TAMs) in STAD." (PMID 33614473, 2020). "This study linked these tumor-promoting functions to suppression of antitumor immunity through the engagement of C5a with C5aR1 expressed on myeloid-derived suppressor cells (MDSC)." (PMID 33271774, 2020). "According to these findings C5aR1-tumor expression was associated with tumor invasiveness, vascular and lymphatic invasion, liver metastasis, and poor outcome in patients with gastric tumors." (PMID 31001273, 2019). "In studying the underlying cellular mechanisms, Markiewski and colleagues first showed that C5a/C5aR1 interaction promotes the migration of MDSCs into tumors and enhances the suppressive capacity of tumor-associated MDSCs." (PMID 31379815, 2019). "Genetic abrogation of C5aR1 in the host dampens M2-polarized tumor associated macrophages, leading to a decrease of liver and lung metastases in a syngeneic colon cancer model." (PMID 31001273, 2019). "The IHC assay results also demonstrated that C5AR1 expression was significantly upregulated in the tumor samples compared with the adjacent-normal samples, indicating that expression of C5AR1 was strongly increased in the STAD and associated with tumorigenesis." (PMID 40193680, 2025). "Moreover, the up-regulation of C5aR1 in cSCC cells and fibroblasts in the tumor microenvironment (TME) was associated with poor prognosis." (PMID 40056975, 2025). "Similarly, in breast cancer, high expression of C5aR1 is associated with larger tumor size, lymph node metastasis, and advanced clinical stages." (PMID 41373839, 2025). "Complement C5a receptor 1 (C5aR1) is associated with both tumorigenesis and tumor-related immunity." (PMID 39368999, 2024). "Moreover, increased C5aR1+ neutrophils were linked to tumor progression and poor survival for BC patients." (PMID 34312368, 2021). "In addition to immune cells, C5aR1 is expressed in neoplastic cells of multiple tumour entities, where C5aR1 is associated with a higher proliferation rate, advanced tumour stage, and poor patient outcomes." (PMID 33606748, 2021). "Interestingly, complement appears to promote tumor angiogenesis, as indicated by reduced vascular density and impairment of endothelial cell function in C3aR-and C5aR1-deficient mice in a transgenic model of ovarian cancer." (PMID 33488603, 2020). "The result may also explain the observation that tumor burden in C5-deficient mice is greater than in C5ar1-deficient mice." (PMID 32754267, 2020). "Moreover, the expression levels of C3, CR4, and C5aR1 were also strongly correlated with various immune marker sets, such as those of tumor-associated macrophages (TAMs), M1 and M2 macrophages, T cell exhaustion, Tregs, and DCs, in STAD." (PMID 33614473, 2020). "The original discovery of tumor-promoting roles of complement linked these complement functions to the complement anaphylatoxin C5a receptor 1 (C5aR1)-dependent regulation of myeloid-derived suppressor cells (MDSC) and their C5aR1-dependent recruitment to tumors." (PMID 33488603, 2020). "Importantly, C5aR1-deficiency and pharmacological blockade of C5aR1 by selective C5aR1 antagonists have been shown to impair tumor growth, pointing to the C5a/C5aR1 signaling axis as an effector mechanism of C-mediated tumor-promoting functions." (PMID 30319647, 2018).
tumor (continued). "In addition to regulating myeloid-origin cells such as MDSC and tumor-associated macrophages (TAM), C5aR1 and the complement anaphylatoxin C3a receptor (C3aR) synergistically impair cytolytic activity of tumor infiltrating CD8+T cells (TIL) by inhibiting expression of IL-10 in these cells." (PMID 33488603, 2020). "The focused blockade of C3ar/C5ar1 GPCR signaling in an intratumoral ISFI opposed solid cancers by jointly repressing cancer cell viability/growth, tumor-associated angiogenesis, and myeloid-derived suppressor cell (MDSC) recruitment." (PMID 42274564, 2026). "In contrast to i.p. administration of C3ar/C5ar1 antagonists to tumor-bearing mice, injecting the antagonists intratumorally in slow release poly (lactic-co-glycolic acid) (PLGA) polymer caused near-complete tumor elimination." (PMID 42274564, 2026). "Univariate analysis of OS revealed significant associations with several factors, including high CA19-9 levels, regional lymph node metastases, high tumour volume, High C5a-C5aR1 c-axis, and High C5a-C5aR1 s-axis." (PMID 41044172, 2025). "In the context to GBM, upregulation of several complements—such as C1q, C3, and C5aR1—has been reported in patient serum, tumor tissues and GBM cell lines." (PMID 40843669, 2025). "While C5aR1, as a component of the innate immune system, is well known to be highly expressed on macrophages and neutrophils, we have previously shown that C5aR1 is also expressed in tumour cells in vivo." (PMID 40695778, 2025). "Staining for C5aR1 was detected on the surface of tumor cells at the invasive edge of human cSCC xenografts in vivo." (PMID 40056975, 2025). "C5aR1 and its ligand C5a are pivotal molecules within the complement system, and their interaction has been shown to regulate tumor growth and immune suppression in various cancers 22,23." (PMID 40225866, 2025). "A recent study has also highlighted the importance of understanding the role of C5aR1 in modulating tumour radiation sensitivity." (PMID 39765018, 2025). "In this study, we demonstrate that increased C5aR1 expression in the hypoxic tumour cells is mediated by the ER stress-driven UPR." (PMID 40695778, 2025). "Subsequent reports have indicated that C5aR1 expressed on MDSCs can also impair anti-tumor T cell responses by binding to ribosomal protein S19 (RPS19)." (PMID 39958348, 2025). "Based on the dual role mechanism of the C5a-C5aR1 pathway in tumor immunity and its potential for clinical translation, related therapeutic strategies are gradually transitioning from basic research to diversified areas." (PMID 41373839, 2025). "In multivariate analysis, regional lymph node metastases, high tumour volume, High C5a-C5aR1 c-axis, and High C5a-C5aR1 s-axis were identified as independent poor prognostic factors." (PMID 41044172, 2025). "A similar trend was also reported in lung cancer-bearing mice, where combining C5aR1 inhibition (W-54011) with irradiation (3 × 8 Gy) synergistically attenuated tumour growth." (PMID 39765018, 2025). "Consistent with previous studies, we found that, at the protein level, C5aR1 was highly expressed in tumour compared to normal tissues in all of the prostate and endometrium sections, and three out of five colorectal sections." (PMID 40695778, 2025). "Pharmacological inhibition using a combination of SB290157 (typically reported as a C3aR antagonist) and anti-C5aR1 monoclonal antibody also restricted tumour growth delay following irradiation in B16F10-OVA-bearing mice." (PMID 39765018, 2025). "We investigated C5aR1 expression in tumour and normal tissue pairs with an in-house tissue microarray (TMA)." (PMID 40695778, 2025). "In tumours with an immunosuppressive microenvironment, we recently found C5aR1 expression on malignant epithelial cells, highlighting potential tumour cell–specific functions." (PMID 40695778, 2025).
tumor (continued). "This study highlights the potential application of LukS-PV in tumor therapy and facilitates the development of antitumor agents targeting complement receptor C5aR1." (PMID 39736396, 2025). "We recently reported that in tumour models with immunosuppressive TMEs, C5aR1 is highly expressed in malignant epithelial cells." (PMID 40695778, 2025). "Elevated expression of C5aR1 was noted in the cSCC tumor cells and stromal fibroblasts compared with AK and cSCCIS in vivo, with the expression increasing toward mcSCC and cSCC metastases." (PMID 40056975, 2025). "Here, we show that physical conditions of the tumour microenvironment leading to immunosuppression, induce C5aR1 expression and control its intracellular localisation." (PMID 40695778, 2025). "Together, these data demonstrate that tMSLC-derived C5a activates C5aR1 signaling in glioblastoma to enhance proliferation, stemness, and invasion, whereas W54011 treatment disrupts this signaling and restores tumor cells to a less aggressive state." (PMID 41353504, 2025). "Taken together, these results suggest that pharmacological inhibition of the C5a-C5aR1 axis reduces hypoxic tumour cell survival, albeit with some notable differences being observed depending on the inhibitor used." (PMID 40695778, 2025). "Specifically, C5aR1 expression was markedly elevated in the tumor tissue derived from patient TS15-88, whereas C5aR2 levels showed no significant variation." (PMID 41353504, 2025). "In agreement with other studies, we observed that C5aR1 protein is highly expressed in tumour tissues compared to normal tissues." (PMID 40695778, 2025). "Local complement activation, such as after radiotherapy, can recruit immune effector cells via the C5a-C5aR1 pathway, enhancing tumor antigen release and promoting immunogenic cell death." (PMID 41373839, 2025). "C5a increased the invasiveness of cSCC cells, and an up-regulation in the expression of C5aR1 was also observed on the tumor cell surface as well as in CAFs." (PMID 40056975, 2025). "Our findings are consistent with recent reports showing that C5 can be cleaved intracellularly in multiple cell types to promote C5a-C5aR1 signalling and tumour progression." (PMID 40695778, 2025). "Intradermal transplantation of HPV16 SCC-derived cell lines into C5aR1+/− versus C5aR1−/− syngeneic hosts showed significantly impeded tumor growth in C5aR1−/− recipients." (PMID 41300283, 2025). "Deletion of C3 or C5aR1 or administration of a C5aR1 inhibitor impaired tumour infiltration of adoptively transferred T cells, increasing tumour cell survival." (PMID 39765018, 2025). "Together, these findings suggest that targeting C5aR1 modulates tumour cell radiosensitivity to improve treatment efficacy, even in the absence of CD8+ T-cell infiltration." (PMID 39765018, 2025). "The C5a-C5aR1 s-axis adversely affects tumour immunity by mobilising MDSCs and enhancing CD8+ T cell suppressive capability." (PMID 41044172, 2025). "Administration of a C5aR1 inhibitor appears to modulate antitumour immunity within both tumour cells and the surrounding stroma, thereby warranting future clinical applications." (PMID 41044172, 2025). "CD8+ T cell function is enhanced by reducing tumor growth in C3aR1KO mice, indicating that C3aR1 and C5aR1 regulate cytolytic activity of tumor-infiltrating lymphocytes (TILs)." (PMID 40309765, 2025). "C5a and C5aR1 expression was observed in the cytoplasm of tumour cells, as well as in the stroma surrounding the PDAC cells." (PMID 41044172, 2025). "In a murine model resistant to ICI, inhibitors of C3aR1 (SB290157) and C5aR1 (PMX53) reduced tumor growth and TIL function, increasing IFN-γ production." (PMID 40309765, 2025). "They found that C5aR1 levels were elevated in ATC tumor samples and correlated with poorer survival outcomes." (PMID 41300283, 2025). "indicating that C5aR1 inhibition suppressed tumor growth by educating TAMs and enhancing TAM-mediated anti-tumor immunity of T cells." (PMID 38331868, 2024).
tumor (continued). "It was found that C5a/C5aR1 axis can alleviate the tumor progression, significantly inhibit pro-inflammatory factors, and induce the production of anti-inflammatory factors." (PMID 38918278, 2024). "To confirm the importance of CD8+ T cells and TAMs in C5aR1 inhibition-mediated tumor suppression, we first deleted CD8+ T cells and found that the lack of CD8+ T cells abolished the inhibitory effects of anti-C5aR1 Ab on tumor development." (PMID 38331868, 2024). "Our studies further credential C5aR1 as a potential therapeutic target that provides an approach to selectively deplete pro-tumor macrophage function while sparing anti-tumor macrophage function resulting in CD8 T mediated inhibition of tumor growth." (PMID 38802355, 2024). "In general, targeting C5aR1 for tumor treatment has considerable potential utility, but the specific mechanism of action involving C5aR1 needs further exploration and study." (PMID 39368999, 2024). "C5a/C5aR1 signaling has been shown to promote tumor progression by recruiting MDSCs in breast malignancies." (PMID 38331868, 2024). "Autocrine stimulation of C3aR and C5aR1, expressed in the tumor cells, promotes tumor proliferation, triggering the phosphoinositide 3-kinase (PI3K)–AKT pathway." (PMID 38339243, 2024). "C5AR1 is known to activate and recruit myeloid-derived suppressor cells to tumors and reshape immunosuppressive tumor microenvironment." (PMID 38729966, 2024). "C5aR1 plays a key role in regulating tumorigenesis in multiple ways including influencing the tumor microenvironment." (PMID 38331868, 2024). "This suggests that high C5aR1 levels limit the ability of immune cells to contribute to efficient anti-tumor activity." (PMID 38802355, 2024). "At the genus level, the relative proportions of Allobaculum, Parasutterella, and Bifidobacterium which have anti-tumor properties, were significantly increased in C5ar1-/- mice bearing tumors." (PMID 38331868, 2024). "To verify that the combination affects the tumor microenvironment, we returned to genetic depletion of C5aR1." (PMID 38458648, 2024). "The number of dendritic cells (DCs) did not change, indicating that CD8+ T cells and TAMs were involved in C5aR1 inhibition-mediated tumor suppression." (PMID 38331868, 2024). "In a model of squamous carcinogenesis, C5a regulated mast cells and macrophages expressing C5aR1+ to exhibit a protumorigenic property, resulting in promoted tumor progression." (PMID 38098230, 2024). "Ligand-receptor analysis between macrophages and tumor cells identify C5/C5AR1,SPP1/ITGA4, and TF/TFRC as the ligand-receptor signaling mechanism driving these niche-DE genes." (PMID 38217002, 2024). "We confirmed that in comparison with para-carcinoma samples, C5aR1 was abundant in both tumor cells and TAMs." (PMID 38331868, 2024). "FMT experiment demonstrated that prophylactic transfer of C5ar1−/− microbiota was able to suppress tumor growth." (PMID 38331868, 2024). "Our data suggested that C5aR1 was present at high levels in TAM_C3 macrophages and CellChat suggested that it was involved in communication between TAM_C3 macrophages and tumor cells." (PMID 38802355, 2024). "The current studies extends these observations to demonstrated that a C5aR1 high macrophage population not only mediates PARPi resistance in T127 but is able to transfer PARPi resistance to the normally T22 PARPi-sensitive tumor at a distance." (PMID 38802355, 2024). "In line with the RPPA data, PMX205 treatment or C5aR1 depletion resulted in increased apoptosis in tumor cells following RT as well as 5-FU and Oxaliplatin treatment." (PMID 37824211, 2023). "The correlation was analyzed between C5aR1 and 22 immune checkpoint-related genes using the TCGA database and Tumor Immune Estimation Resource (TIMER)." (PMID 36508191, 2023). "Together, these data suggest that C5aR1 mediates tumor cell prosurvival signaling, with NF-κB acting as a key regulator of this response." (PMID 37824211, 2023).